NOD1 (nucleotide binding oligomerization domain containing 1)
Diseases named in the same sentence as NOD1 in open-access papers (continued):
Sharing a sentence is not in itself a finding about the gene and the disease.
infection (141 papers, 2006 to 2026). The state of being infected such as from the introduction of a foreign agent such as serum, vaccine, antigenic substance or organism. "In zebrafish models, infection with spring viremia or carp virus (SVCV) showed that larvae deficient in NOD1 demonstrated a significant impairment in their antiviral immune response." (PMID 39878363, 2025). "Infected blood-MØs evidence strong upregulation of membrane-associated TLR4 and cytoplasmatic NOD1 during the first 3 h of infection." (PMID 35053098, 2022). "It should be noted that this sensing mechanism can also lead to adverse effects, as it was shown that ER stress can increase the susceptibility of HeLa cells to infection with S. Typhimurium, likely due to NOD1 hyperresponsiveness." (PMID 35967403, 2022). "When assessing the severity of a CT infection, Branković’s study found that carrying the NOD1 GG insertion increased the risk of tubal pathology (OR: 2.25; 95%CI: 1.08–4.67, p = 0.04)." (PMID 33430411, 2021). "Prematurity has been strongly associated with infection, and there are studies that go further and relate it to the activation of NOD1 by bacterial ligands sensing." (PMID 34066406, 2021). "Then, we found that NOD1 showed a significant expression difference between the livers of susceptible and resistant individuals after infection with DHAV-3, with higher expression in the SZ7 flock." (PMID 34745142, 2021). "While these previous results are somewhat discordant with our present data, it should be noted that the enhanced shedding of bacteria was modest in double NOD1/2-deficient mice and only detectable during the early stage of infection." (PMID 32487756, 2020). "NOD1-deficient mice are susceptible to infection with Staphylococcus aureus and Helicobacter pylori." (PMID 25722880, 2015). "Colonization and inflammation induced by infection with wild-type S. Typhimurium bacteria in Nod1- or Nod2-deficient mice was similar to C57Bl/6 mice, which is in agreement with a previously published report." (PMID 25423082, 2014). "After infection, real-time PCR was performed to determine the presence of mRNAs encoding NOD1 and NOD2." (PMID 25443778, 2014). "Here, we demonstrate that wild-type, Nod1-, Nod2-, Nod1/Nod2- and Rip2-deficient mice displayed similar levels of local chemokines, neutrophil recruitment to the infection site, local and systemic bacterial loads and survival." (PMID 25084278, 2014). "mice deficient in Nod1 are more susceptible than wild-type mice to infection by cag-positive strains of H. pylori." (PMID 24216700, 2013). "Thus, the ER stress and subsequent NOD1/2-dependent inflammation caused by Chlamydia opposingly contributes to infection clearance." (PMID 34201509, 2021). "Furthermore, NOD1 mRNA is suppressed in monocytes of septic patients, increasing the risk of infections." (PMID 34066406, 2021). "MEFs from Nod1-deficient mice were demonstrated to be defective in targeting L. monocytogenes to autophagosomes, indicating an important role for peptidoglycan recognition in the induction of autophagy during infection with this bacterium in mammals as well." (PMID 29875765, 2018). "Our results reveal that NOD1 activation induces an antibacterial state in AMs, which may improve the control of intracellular pathogenic infections." (PMID 25253572, 2014). "Nod1 and Nod2 receptor mediated recognition, together with the susceptibilty to penicillin, suggests that cell wall precursors/peptidoglycan fragments are synthesized by Chlamydiaceae during infection." (PMID 24616885, 2014). "The cag PAI-encoding strain of H. pylori used in our infection experiments induces a Nod1-mediated proinflammatory response capable of affecting Helicobacter loads in the mouse, but the source of PG fragments delivered to host cells by the Cag T4SS is not clear." (PMID 22457625, 2012).
infection (continued). "Despite normal cytokine production in the sera, NOD1(−/−) mice were highly susceptible to this infection, as judged by the high parasite load in spleen and heart tissues and succumbed to the infection in a similar way to Myd88 and nitric oxide synthase (iNOS) knock-out mice." (PMID 21869919, 2012). "We hypothesize that DHAV-3 infection likely trigger the NOD1 signaling pathway, causing the type I interferon gene and cytokine expression levels to be significantly upregulated, which resulted in an aggravated inflammatory response and liver damage and eventually led to the death of ducklings." (PMID 34745142, 2021). "Therefore, as the molecular details of the PGN-Nod1 relationship are not yet elucidated, we are not able to clarify the mechanisms underlining the reduction of Nod1 activation observed with the PGN of the P. aeruginosa strains isolated from the chronic stage of the infection." (PMID 20037649, 2009). "SEAP was detected in the supernatants of infected cells at elevated levels at 24 and 48 hours post infection (hpi) for NOD1, however, NOD2 signaling appeared to be delayed as SEAP was only present at appreciable levels in cell supernatants at 48 hpi." (PMID 40502116, 2025). "In this same fish species, NOD1 expression in the intestine increased ~6-fold at 3 days post-infection with Edwardsiella ictaluri." (PMID 40963628, 2025). "The genes specifically downregulated over the course of infection by Fasciola miRNAs included Nod1, E2f1, Tnfaip3 and Cdk6 at 6 hrs, and Jam3, Vegfa, Nod1, Uvrag and Nlrc3 at 18 hrs." (PMID 39344634, 2024). "Violin plots demonstrate that Nod1, Nod2 or Ripk2 were expressed by very few ME cells of any category, prior to NTHi infection." (PMID 35903351, 2022). "In conclusion, our results demonstrate that M. hyopneumoniae activates the NOD1-RIP2 pathway and is co-localized with host NOD1 during infection." (PMID 35873172, 2022). "The UPR and NOD1/2 are connected in a variety of different infections and understanding how these connections influence the host has implications outside infectious disease research." (PMID 34748367, 2022). "Although previous study has shown that NOD1 impacts larvae survival via CD44a20, the functions of piscine CD44a and the correlation between NOD1 and CD44a receptors in pathogen infection are unreported." (PMID 36042265, 2022). "M. hyopneumoniae infection up-regulated the expression of NOD1 compared with the mock infection control." (PMID 35873172, 2022). "In teleost, our previous study showed that NOD1-RIPK2 signaling regulated the expression of CD44a19–21, however the role of the correlation between CD44 and NOD1 in resisting pathogen infections is unclear." (PMID 36042265, 2022). "In a study to investigate the role of Nod1, organoids generated from Nod1 knockout mice had increased expression of NF-KB target genes compared to WT C57BL/6 mice after infection with H. pylori strains PMSS1 and 7.13 for 6 and 24 hours." (PMID 35269931, 2022). "Infection of NOD1/2 KO mice with wildtype of B. abortus or infection of wildtype mice with the VceC null mutant yields decreased IL6 production, milder pathology and increased survival of mice." (PMID 34201509, 2021). "In yellow catfish, both tlr5M and nod1 mRNAs were induced notably and continuously in the liver from 6 h or 12 h to 120 h post-infection, and the predicted protein structures of two genes were similar to those of mammals." (PMID 33732247, 2021). "This together with our evidence on NOD1/2 activation by S1P via the NBDs substantiates the potential relevance of metabolites as primordial signals for infection." (PMID 33942347, 2021). "Four well-described SNPs that have previously been associated with the outcomes of a CT infection are: TLR2 +2477 G > A (rs5743708), NOD1 + 32656 T −> GG (rs6958571), CXCR5 + 10950 T > C (rs3922), and IL10 − 1082 A > G (rs1800896)." (PMID 33430411, 2021).
infection (continued). "During infection, NOD1 and/or NOD2 represent an intracellular surveillance system inducing NF-κB activation by detecting cytoskeleton disruption, instead of monitoring RHO GTPases." (PMID 34201509, 2021). "I: We observed that CT positive women with the NOD1 GG insertion were more likely to have a symptomatic course of infection (OR: 1.9, 95%CI: 1.1–3.4, p = 0.02) as compared to an asymptomatic infection." (PMID 33430411, 2021). "NOD1 plays an important role in response to pathogen infection to induce activation of intracellular signaling pathway, leading to pro-inflammatory response." (PMID 33646441, 2021). "In a study focused on factors that make cells more susceptible to Salmonella enterica serovar Typhimurium infection, it was found that ER stress inducers that engage PERK made cells more responsive to infection in a NOD1-dependent manner." (PMID 33503814, 2021). "Many intracellular pathogens, such as Legionella pneumophila and Burkholderia pseudomallei, secrete S1P lyases as virulence factors facilitating intracellular survival, supporting the importance of S1P sensing by NOD1/2 during intracellular infection." (PMID 33942347, 2021). "In another in vivo study in mice, the preactivation of NOD1 previous to infection by H. pylori reduces the frequency of adenocarcinoma and inflammation score." (PMID 33879265, 2021). "In this study, we are able to attenuate the effects of C12-induced NOD1 activation in an infection/inflammation model of cancer metastasis at two different levels: NOD1 at the receptor level with ML130 and p38 the major signaling molecule with BIRB0796." (PMID 31956962, 2020). "NOD1/NOD2-deficient mice displayed a modest impairment of bacterial clearance, as evident by higher bacterial shedding during the early stage of infection." (PMID 32487756, 2020). "Coupled with survival analyses from RNA-Seq and TMA immunohistochemistry, these data strongly argue a role for NOD1 in infection-mediated cancer metastasis and thereby clinical recurrence." (PMID 31956962, 2020). "Our previous results showed a role for NOD1 and NOD2 in abortion caused by B. abortus in mice, as mice deficient for both NOD1 and NOD2 had reduced inflammation and increased viability of pups after infection." (PMID 31337727, 2019). "The expression of NOD1 increased remarkably in the liver after infection with V. anguillarum, V. harveyi, and LPS-B5." (PMID 30013548, 2018). "Bioluminescence imaging of the luciferase-expressing Aspergillus within the mice suggests that Nod1−/− mice more efficiently clear the fungi from the lung, whereas WT mice developed a progressing infection as indicated by the increasing luminescence signal." (PMID 29326692, 2017). "One study showed that ectopically expressed human NLRP10 colocalizes with NOD1 in HeLa cells upon infection with Shigella flexneri." (PMID 29163529, 2017). "Again, contrary to our data, ER stress contributes to inflammation during an infection with Brucella abortis in a NOD1/NOD2 dependent manner and the unfolded protein response has been shown to strengthen NF-κB dependent inflammation." (PMID 28545453, 2017). "Monomeric PG fragments have been shown to promote ciliated cell death and sloughing in human Fallopian tube explants during infection with GC, and the presence of cell-free supernatant alone is sufficient to activate a NOD1-dependent NF-κB response." (PMID 29042497, 2017). "Although at 8h post infection both NOD1 humanized mice and NOD1KO mice showed the same load of bacteria, the humanized mice harbored significantly fewer leptospires than mNOD1KO at 24h post infection." (PMID 29211798, 2017). "Upon activation during infection, NOD1/2 and Dectin-1 promote cytokine production, with subsequent clearance of pathogens." (PMID 26581487, 2015). "Nod1 (C10) and its responsive genes Irf7 and Stat1 (C11) were elevated late during infection as well as interferon-induced genes Cxcl10, Ifit1-3, Iigp1 and Rsad2 (C7)." (PMID 26367386, 2015).
infection (continued). "This validated that silencing of SSH1 significantly impaired NOD1-mediated responses in human cells triggered by TriDAP and infection with the invasive bacterial pathogen S. flexneri." (PMID 25187968, 2014). "Based on experimental data it is assumed that the infection leads via TLR or NOD1 signaling to an activation of host MAP-kinases (e.g., p44/42 and p38) as well as the NFκB pathway and subsequently to an induction of a pro-inflammatory immune response." (PMID 24783060, 2014). "This is in contrast to recent evidence that suggested IL-1β expression and secretion after infection of human trophoblasts with C. trachomatis was dependent upon intracellular NOD1." (PMID 25010668, 2014). "In this model, detection of cytosolic access by the S. Typhimurium T3SS-1 through the NOD1/2 signaling pathway contributes to intestinal inflammation early during infection." (PMID 24992093, 2014). "An effect of Nod1 on survival of S. flexneri was documented only at 6 hr of infection, raising the possibility that the events described by these authors early during infection are part of the same process we describe here." (PMID 24722587, 2014). "We demonstrate that S. Typhimurium ΔmsbB infection triggered exacerbated inflammation in Nod1−/−, Nod2−/− and DKO mice compared to C57BL/6 mice." (PMID 25423082, 2014). "We infected AMs with Mtb as a model intracellular pathogen and evaluated the effect of NOD1 activation as an inducer of autophagy after an established infection." (PMID 25253572, 2014). "It was demonstrated that the band density of NOD1 continuously increased after prolonged infection by P. aeruginosa, while other autophagy proteins (e.g. NOD2, Beclin1 or Atg5) had the same band density even after prolonged infection." (PMID 25433669, 2014). "Our data show for the first time that lethal infection is associated with the upregulation of surface and intracellular PRRs, including TLR2, Nod1, and Nod2." (PMID 23526993, 2013). "NOD1 and NOD2 contain multiple LRRs, a motif that has been linked to resistance to infection and is found in TLRs and plant R proteins." (PMID 23162548, 2012). "Here, we demonstrated that macrophages from NOD1-, NOD2-, and Rip2-deficient mice produced lower levels of TNF-α following infection with live Brucella abortus compared to wild-type mice." (PMID 22203860, 2012). "In fact, for certain infections, impairment of NOD1 and NOD2 function interferes with both innate and adaptive immune responses." (PMID 23162548, 2012). "The infection of AGS cells in the presence of siRNA specific for NOD1 resulted in the impaired nuclear translocation of Stat1 and production of IFN-β and IP-10, but unchanged nuclear translocation of NF-κB subunit, p65." (PMID 21152124, 2010). "Infection with cag-PAI-positive H. pylori leads to the activation of NOD1 in gastric ECs and to the induction of several host defense factors including hBD2, IFN-β, and IP-10, all of which regulate bacterial growth." (PMID 21152124, 2010). "In agreement with the in vitro data, both Nod1−/− and Nod2−/− mice displayed delayed pulmonary bacterial clearance compared to WT controls, as reflected by significantly higher bacterial counts in Nod1−/− and Nod2−/− mice at 5 days post-infection." (PMID 19360122, 2009). "Transcriptional activation of the protein produced by NOD1 (Nod1) was studied after infection of Caco2 cells with Escherichia coli LF82." (PMID 19327158, 2009). "Infection with this bacterial strain leads to increased Nod1 m RNA levels for the 6 h time point (4.3 fold increase as measured using quantitative real time PCR), whereas after 9 h infection the Nod1 expression levels were similar to the uninfected state." (PMID 19327158, 2009). "According to our data the infection of Caco2 cells with the adherent-invasive Escherichia coli (AIEC) strain LF82 leads to the transcriptional activation of Nod1." (PMID 19327158, 2009).
infection (continued). "After infection of pulmonary epithelial cells with S. pneumoniae, expression of NOD1 and NOD2 increased in these cells in vitro and overall expression was up-regulated in mouse lungs infected with pneumococci." (PMID 16827942, 2006). "One study in orange-spotted grouper (Epinephelus coioides) found that NOD1 was slightly upregulated following infection with the nervous necrosis virus (NNV), but acts as a negative modulator of IFN signaling at the RNA sensor level by suppressing RIG-I- and MDA5-mediated IFN promoter activation." (PMID 40963628, 2025). "In addition, all seven experimental groups were compared to the control group in terms of genes related to infection and inflammation, such as NOD1 and NOD2." (PMID 39474054, 2024). "Our results showed a positive modulation of the NOD1, NOD2, and NLRP3 genes after 24 h of co-culture, suggesting that in the early stages of infection, the transcription of these genes may be associated with the transcription of the TLR genes." (PMID 38248981, 2024). "Our data show that NOD1 is an important regulator of bioactive IL-18 production by epithelial cells in response to the infection and, moreover, that this NLR plays a protective role in tissue homoeostasis through its control of cell proliferation and apoptosis." (PMID 37365163, 2023). "nod1 and nod2 play fundamental and pleiotropic roles in host defense against infection." (PMID 36991462, 2023). "Furthermore, EO supplementation also improved the expression of pattern recognition receptor genes such as TLR2A and NOD1, which detect infection and trigger inflammation to defend against pathogens." (PMID 37630519, 2023). "Previous studies have revealed a critical role of NOD1 in innate immune response and inflammatory regulation during infection by Pseudomonas aeruginosa, Streptococcus pneumoniae and other intracellular bacteria such as Shigella flexneri or Listeria monocytogenes." (PMID 35873172, 2022). "We can speculate that the sensing of the S. Enteritidis infection by NOD-1 can lead to the production of IFN-α that controls the level of colonization and infection by the pathogenic bacteria in the chicken cecum." (PMID 35846741, 2022). "Upon infection, NOD1 expression can be regulated by a variety of mechanisms." (PMID 35638852, 2022). "Thus, it is increasingly clear that infection responses mediated by NOD1 and/or NOD2 to promote inflammation is critical to control enteric infections, such as C. rodentium." (PMID 34748367, 2022). "Therefore, it has been proposed that reduced TCT production, and reduced NOD1 and NOD2 activation by N. meningitidis strains is a disadvantage during infection, whereby cytotoxicity and inflammation are associated with the effective establishment of infection." (PMID 35967403, 2022). "NOD1 regulates neutrophil function and promotes a rapid response to infection by recognizing microbial peptidoglycans, and its expression pattern may reflect the innate immune differences between the large and small intestines." (PMID 36359049, 2022). "For example, M. tuberculosis reduces NOD1 activation by peptide-amidation of PGN fragments, which may be a mechanism to reduce the host inflammatory response in a NOD1-dependent manner in order to establish an effective infection in the host." (PMID 35967403, 2022). "NOD1 is an intracellular receptor that, when activated, induces gene expression of pro-inflammatory factors promoting macrophages and neutrophils recruitment at the infection site." (PMID 34060399, 2021). "Therefore, there is an obvious link between the immune system, nutrition, vaccination, NOD1, and infection that needs to be investigated in depth." (PMID 34066406, 2021). "NOD1/NOD2 depletion affected bacterial clearance in early infection." (PMID 32487756, 2020). "From these data, it is clear that NOD1 participates in systemic inflammation and infection, whether through its own activation or in conjunction with other PRRs." (PMID 31956962, 2020).